ENSG00000289855 (novel transcript)
Gene: Long non-coding RNA gene on chromosome 2 (61,763,893 to 61,766,653, forward strand). Ensembl gene ENSG00000289855.
Gene Ontology:
Biological process: SRP-dependent cotranslational protein targeting to membrane, signal sequence recognition
Cellular component: signal recognition particle, endoplasmic reticulum targeting